IL6 (interleukin 6)
Diseases named in the same sentence as IL6 in open-access papers (continued):
Sharing a sentence is not in itself a finding about the gene and the disease.
Hypertension (continued). "PC4d was also associated with pro-inflammatory markers such as hsCRP, IP-10, IL-6 and VCAM-1, and weakly with prednisolone treatment, but not with traditional cardiovascular disease risk factors, e.g. age, gender, current smoking and hypertension." (PMID 32259250, 2020). "However, random allocation to canakinumab, a drug that inhibits IL-1β and reduces both IL-6 and hsCRP, did not reduce the development of incident hypertension nor reduce blood pressure at 3, 6, or 12 months." (PMID 31884854, 2020). "Thus, in young-onset hypertension, elevated levels of MCP-1 and IL-6 in the vascular endothelium may indicate the stimulation of cellular immunological processes that contribute to early vascular aging and the development of hypertension." (PMID 31655529, 2019). "Furthermore, our results showed that high blood pressure led to increases in the expression of RANKL/OPG ratio, IL-6 and M-CSF, all of which could promote osteoclast formation and activity that positively influencing bone resorption." (PMID 31444374, 2019). "TNF-α and IL-1β levels, counter regulated by IL-6 and soluble TNF-α receptor/soluble TNF-α receptor 2 (sTNFR1/sTNFR2) by TNF-α, correlate with impaired endothelium-dependent dilatation and induction of insulin resistance followed by high blood pressure, respectively." (PMID 31671730, 2019). "Indeed, in that study only the baseline levels of sVCAM-1 (but not sICAM-1, CRP, IL-6 and TNF-α) were associated with the 15 year cumulative incidence of hypertension." (PMID 29101422, 2018). "This included lower levels of insulin, glycated hemoglobin, blood glucose, inflammatory markers (IL-6 and CRP), and hemostatic factors (von Willebrand factor, factor VIII, tPA antigen, and D-dimer); a smaller waist circumference; and higher lung function and reduced odds of hypertension." (PMID 30124747, 2018). "Besides the independent variables included in multivariable models, age, hypertension, eGFR and IL-6 were tested in univariable model, however they did not reached p<0.10 and were not included in the multivariable model." (PMID 30118483, 2018). "Nonetheless, it is clear that IL-6 does not contribute to basal or resting blood pressure whereas IL-6 appears to contribute, in part, to the increase in blood pressure produced in experimental hypertension, including that produced by angiotensin II." (PMID 29186034, 2017). "However, median values of IL-6 and TNF-α in T2DM + HTN group compared with T2DM group suggests that co-morbidity with hypertension may possibly have a cumulative effect." (PMID 26391589, 2015). "We found that NE upregulated the expression of VEGF, IL-8 and IL-6 in vitro and stimulated tumor growth in vivo, which was mediated by β-AR/cAMP/PKA signaling pathway and could be inhibited by propranolol, a β-blocker for hypertension for decades." (PMID 24555849, 2014). "The effect of medication on the abundance can be demonstrated by IL-6, where the distribution of protein level was clearly shifted upwards with the use of dihydropyridine derivatives (ATC: C08CA) found in drugs prescribed for treatment of hypertension or angina pectoris." (PMID 25147954, 2014). "We also show that medications used to treat, for example, hypertension such as dihydropyridine derivatives, but not ACE-inhibitors or selective β-blockers agents, cause or maintain an increase in the inflammatory response cascade via high IL-6 levels." (PMID 25147954, 2014). "However, our data shows that T2DM patients with hypertension had significantly lower levels of IL-β and Caspase-1 and slightly higher levels of IL-6 and IL-10, compared to patients with no hypertension." (PMID 23762057, 2013). "However, IL-6 knockout mice were not protected against the aldosterone-dependent hypertension." (PMID 39723211, 2024).
Hypertension (continued). "As expected, the levels of the inflammatory cytokines IL-6 and TNF-α were elevated in the aortas of HFpEF pigs and significantly decreased with dapagliflozin treatment, suggesting that dapagliflozin could attenuate the hypertension-induced macrovascular inflammatory response." (PMID 31429767, 2019). "In addition to IL-6, MCP-1, a key chemokine involved in the onset of inflammation, may play a role not only in various pathophysiological processes occurring in the cardiovascular system but also in the development of arterial hypertension." (PMID 31655529, 2019). "Interestingly, this was the only hypertension medication that is correlated with higher IL-6 levels, and neither angiotensin-converting-enzyme (ACE)-inhibitors (ATC: C09AA), selective β-blocker agents (ATC: C07AB) nor a combination of these mediate this effect." (PMID 25147954, 2014). "Moreover, the mRNA expression of IL-1β and IL-6, intercellular/vascular cell adhesion molecules (ICAM, VCAM) and monocyte chemoattractant protein (MCP-1), have been reported to be enhanced in aortas of hypertensive rats, and in cardiac tissue from different rat models of hypertension." (PMID 20462420, 2010). "Recent evidence suggests that markers such as interleukin-6 (IL-6) and pentraxin-3 (PTX-3) are elevated in patients with obstructive sleep apnea (OSA), even in the absence of hypertension." (PMID 40428013, 2025). "Increases in IL-6 and hs-CRP predict incidence of hypertension in older individuals without cardiovascular disease." (PMID 37324636, 2023). "In OSA patients with hypertension, OA did not affect circulating inflammatory marker levels (white blood cells count, CRP, IL-6, IL-10, and TNF-a)." (PMID 35866792, 2022). "VNS has not yet been tested in human hypertension, but has been used in epilepsy and in RA, demonstrating lowering of circulating TNF-α, IL-1-β, and IL-6 levels and improvement in disease activity." (PMID 34698811, 2021). "Inflammatory markers such as hsCRP and IL-6 are increased in PWH with MetS compared with those without MetS [2••], suggesting that inflammation of MetS plays a role in the pathogenesis of hypertension in PWH." (PMID 32880756, 2020). "Since in IUGR (without coexisting hypertension) no sign of inflammation was noted, i.e., the levels of TNF-α, IL-6, and IL-8 were comparable to normal controls, chronic oxidative stress in the pathology is not very probable." (PMID 32685085, 2020). "Correlations among age, weight, BMI, IL-6, IL-8, TNF-α and TGF-β within group 1 (patients with hypertension without CAD)." (PMID 28033321, 2016). "Correlations among age, weight, BMI, IL-6, IL-8, TNF-α and TGF-β within group 3 (CAD patients without hypertension)." (PMID 28033321, 2016). "The results also revealed that serum levels of IL-6 and TGF-β were significantly decreased and increased, respectively, in the studied groups when compared to control group (without hypertension and CAD)." (PMID 28033321, 2016). "There are very limited studies conducted in Ghana to assess the correlation of IL-6 and TNF-α among T2DM patients with hypertension and non-diabetic participants in rural and urban settings." (PMID 26391589, 2015). "Survivors compared to non-survivors were more likely to have hypertension; higher mean MMSE scores; higher serum albumin levels; and lower mean serum levels of CRP, IL-6, and ET-1." (PMID 26289439, 2015). "Multiple regression analysis revealed significant individual contribution of HOMA-IR, AI, IL6, hsCRP, TNFα, TBARS and hypertension status, but not BMI to the LF-HF ratio in the study group." (PMID 24265679, 2013). "Accumulated visceral adipose tissue produce and secrete a number of adipocytokines, such as leptin, tumor necrosis factor-α (TNF-α), interleukin-6 (IL-6), angiotensinogen, and non-esterified fatty acids (NEFA), which induce development of hypertension." (PMID 18416854, 2008).
Hypertension (continued). "As our study did not measure IL-6 and PTX-3, directly assess endothelial function, or stratify patients based on hypertension status, we could not explore these potentially important differential inflammation patterns." (PMID 40428013, 2025). "The IL-6 behaved similarly to TNF-α with a significant increase in subjects with hypertension, 235.3 pg/mL (83.1–482.4 pg/mL), p < 0.01 compared to subjects without hypertension, 64.9 pg/mL (50.6–247.9 pg/mL)." (PMID 36671026, 2023). "After adjusting for covariates such as age, gender, BMI, FBG, TNF-α, IL-6 and hs-CRP, GLM analyses showed that subjects with PWV and hypertension progression had higher baseline PWV, follow-up PWV and △PWV than those with no PWV and hypertension progression." (PMID 29433526, 2018). "Indeed, OSA patients with hypertension show reduced values of IL-10 accompanied by increased levels of TNF-α, IL-6, and CRP with respect to patients without high blood pressure." (PMID 25944984, 2015).
asthma (806 papers, 2006 to 2026). "Clinically, increased IL-6 levels are associated with severe disease with more frequent exacerbations, lower lung function, and poorer asthma control." (PMID 39714726, 2025). "High IL-6 was a risk factor for poor pulmonary function and acute exacerbation in asthma and the development of acute myocardial infarction." (PMID 40217808, 2025). "IL-6 is produced by macrophages and dendritic cells, which are critical sources of pathogenic IL-6 in asthma." (PMID 40872499, 2025). "We also aimed to show that high IL-6 is associated with asthma severity, as assessed by lung function measures." (PMID 39714726, 2025). "Multiple factors were significantly associated with high IL-6, in the univariable logistic models, including race, sex, metabolic dysfunction, and active asthma." (PMID 39714726, 2025). "A study from the USA evaluating a severe asthma cohort revealed that the plasma concentration of IL-6 was associated with exacerbation of asthma in obese individuals, and that IL-6 concentration correlated with BMI in this cohort." (PMID 40589493, 2025). "Children with asthma tend to have a higher prevalence of IR compared to those without asthma, with IR levels correlating with proinflammatory markers like leptin and IL-6, which are associated with increased airway obstruction and reduced lung volumes." (PMID 40426941, 2025). "In the univariable models, female sex, Black race, BMI, and CRP were positively associated with the odds of high IL-6 asthma, while FEV1 was negatively associated with the odds of high IL-6." (PMID 39714726, 2025). "Previous research has indicated that increased levels of IL-5, IL-6, and IL-8 are associated with heightened air pollution, potentially contributing to asthma, cardiovascular diseases, and metabolic risks." (PMID 40611827, 2025). "In the brain, each 10-fold increase in IL-6 sRa [1.29 (95% CI 1.15–1.45)] was associated with an increased risk of asthma, while an increase in Layilin [0.61 (95% CI 0.51–0.73)] was found to be protective." (PMID 39806440, 2025). "In patients with asthma, IL‐6 levels are associated with ventilation parameters and disease control." (PMID 41179970, 2025). "We developed an IL-6 cut-off model to examine the association between high IL-6, race, high body mass index (BMI), metabolic disease, and asthma severity as assessed by reduced lung function." (PMID 39714726, 2025). "Increased IL-6 levels are also correlated with increased BMI in children and an association has emerged between IL-6 and the likelihood of asthma exacerbation." (PMID 40559430, 2025). "The present letter examined serum IL-6 levels in children and adolescents with asthma and their associations with BMI and the presence of obstructive disorders for the first time." (PMID 40696834, 2025). "CXCL1 is one of the most associated hub genes in the pathogenesis of severe asthma, which can be induced by IL-1β, IL-6 and so on." (PMID 38459541, 2024). "The dominant model (CC + GC) of the IL-6 gene (-174G/C) polymorphism was significantly associated with severe asthma and influencing type 2 inflammatory markers." (PMID 38388670, 2024). "Recent preclinical experiments have demonstrated that a maternal asthma-allergy model is causative of autism-related behaviors in mouse offspring; and cytokines, particularly interleukin (IL)-6, have been proposed to be key mediators of this relationship." (PMID 37661216, 2024). "In individuals with asthma, a higher BMI is closely linked to increased oxidative stress and elevated levels of interleukin-6, along with other proinflammatory markers." (PMID 39596970, 2024). "IL-6 deficiency, in an experimental murine model of asthma, exacerbates disease processes, leading to lung inflammation and tissue damage with an increased TGF-β1production." (PMID 38814518, 2024). "A more extensive analysis included 746 asthmatic patients and 1145 controls and investigated the link between the IL-6 gene (− 174G/C) polymorphism variant and asthma risk." (PMID 38388670, 2024).
asthma (continued). "While a connection has been established between serum interleukin-6 (IL-6) levels and the IL-6 gene (− 174G/C) polymorphism in allergic diseases such as asthma, its specific association with severe asthma remains unexplored." (PMID 38388670, 2024). "The use of dominant model of IL-6 gene − 174G/C polymorphism (CC + CG vs GG) showed that (CC + CG) increased the likelihood of severe asthma fourfold, OR = 4.4, p < 0.001." (PMID 38388670, 2024). "The results reported a significant association between IL-6 gene (− 174G/C) polymorphism and asthma risk, specifically in the recessive and homozygote comparisons." (PMID 38388670, 2024). "The dominant model of IL-6 -174G/C gene (CC + CG vs GG) showed that the risk of mild asthma decreased fourfold, OR = 4.4, p < 0.001, while the recessive model (CC Vs CG + GG) showed insignificant association, p = 0.32." (PMID 38388670, 2024). "One study observed a significant relationship between IL-6 at baseline and the risk of asthma exacerbations requiring systemic corticosteroid therapy." (PMID 38365763, 2024). "Genome-wide association studies and other basic research have shown an association between IL-6 signaling and asthma, which is also supported by clinical studies; and there is growing evidence of subgroups of type 2-low asthma where IL-6 plays a major role." (PMID 39765793, 2024). "IL-6 is a marker of systemic inflammation, obesity, and metabolic dysfunction, and its signaling has been linked to severe asthma." (PMID 39194521, 2024). "To date, there is a notable gap in research addressing the inflammatory implications of IL-6 gene -174G/C polymorphism in adult asthma, particularly within Kuwait and the Gulf region." (PMID 38388670, 2024). "This study illuminated the intricate relationship between the IL-6 gene polymorphism, type 2 inflammation markers, and diverse risk factors in shaping asthma severity." (PMID 38388670, 2024). "Among patients with asthma, an elevated BMI is associated with increased oxidative stress and increased levels of interleukin-6, interleukin-5, interleukin-13, and C-C chemokine receptors." (PMID 39272654, 2024). "Further studies revealed that azithromycin treatment reduces key sputum cytokines associated with non-T2 asthma, such as IL-6 and IL-1β." (PMID 39194521, 2024). "In contrast, Th2-low asthma is mediated by IL-17 and associated with IL-6, which is related to Th17 differentiation and therefore IL-17 secretion, and TNFα." (PMID 39239645, 2024). "Toluene (parent compound of BMA) is thought to cause asthma by activating the IL-6 signaling pathway." (PMID 38317969, 2024). "While IL-6 promotes the production of other cytokines related to atopy and asthma and causes myocardial failure and skeletal muscle atrophy dose-dependently, it also crosses the brain-blood-barrier and placenta." (PMID 39553377, 2024). "For simplicity, this study adopts a dichotomous model where high TGF-β activity in conjunction with IL-1β and IL-6 is linked to asthma, metabolic dysregulations, and an elevated risk of cancer, while it is inversely associated with the occurrence of AR." (PMID 38629073, 2024). "This study examined the relationship between the IL-6 (− 174G/C) gene polymorphism and mild and severe asthma, focusing on its influence on type 2 inflammation." (PMID 38388670, 2024). "In a smaller study, patients with infantile asthma were shown to have a strong correlation with IL-6 gene (-174G/C) polymorphism; the likelihood of asthma increased up to fourfold, especially in the atopic phenotype." (PMID 38388670, 2024). "This asthma endotype is commonly associated with elevated neutrophilic inflammation and increased interleukin (IL)-6 and -17 levels." (PMID 38474191, 2024). "We focused on two commonly implicated pro-inflammatory cytokines, IL-8 and IL-6, which are directly associated with the pathophysiology of non-T2 asthma." (PMID 39538061, 2024).